MBL2 (mannose binding lectin 2)
Diseases named in the same sentence as MBL2 in open-access papers (continued):
Sharing a sentence is not in itself a finding about the gene and the disease.
lymphoma (6 papers, 2018 to 2025). A malignant (clonal) proliferation of B- lymphocytes or T- lymphocytes which involves the lymph nodes, bone marrow and/or extranodal sites. "The first possible association of MBL2 gene 3′-untranslated region polymorphism with cancer (lymphoma) in Caucasians was noted." (PMID 30294330, 2018). "Furthermore, polymorphisms of the MBL2 gene exon 4 3′-UTR seemed to influence the risk of developing lymphoma." (PMID 32635486, 2020). "Additionally, we reported the first possible clinical association of a MBL2 3′-UTR polymorphism (protective effect of “gt1” from lymphoma) in Caucasians." (PMID 30294330, 2018). "The Mannose-Binding Lectin 2 (MBL2) mouse model, utilizing C57BL/6 mice as a syngeneic platform, creates an auto transplantation model for CTCL by injecting MBL2 lymphoma cells and inducing inflammation with dinitrofluorobenzene (DNFB)." (PMID 38665428, 2024). "A murine model was developed after injection of MBL2 T lymphoma cells followed by inflammatory peptide inoculation into the ears, resulting in a local development of lymphoma." (PMID 33106625, 2021). "The authors injected MBL2 T lymphoma cells into the ears of mice and induced lymphoma development by application of di-nitro-fluorobenzene." (PMID 34685762, 2021). "Furthermore, our study identifies CIITA, LYZ, MBL2, and CD40 as potential therapeutic targets for various types of lymphoma treatment." (PMID 40360443, 2025).
myocardial infarction (6 papers, 2012 to 2024). Gross necrosis of the myocardium, as a result of interruption of the blood supply to the area, as in coronary thrombosis. "Proteins involved in the complement and coagulation cascades, like MASP2, CRP, FCN3, and MBL2, were elevated, underlining the known importance of innate immunity and inflammation early in myocardial infarction." (PMID 39513871, 2024). "Based on a pilot study, we hypothesized that functional polymorphisms in the MBL gene (MBL2) leading to dysfunctional protein are related to development of myocardial infarction (MI)." (PMID 22848725, 2012).
type 2 diabetes (6 papers, 2013 to 2025). "The rs1800450 and rs11003125 SNPs of the MBL2 gene have strong linkage disequilibrium and are associated with type 2 diabetes in the North Chinese Han population." (PMID 24376633, 2013). "Their result demonstrated that in both Native Americans (number = 3723) and Old Order Amish (number = 486), the rs1800450 and rs11003125 SNPs (from nineteen tag SNPs of MBL2 gene) contributed to type 2 diabetes susceptibility." (PMID 24376633, 2013). "This evidence proved the association of MBL2 gene with type 2 diabetes from another aspect." (PMID 24376633, 2013). "Few studies have discussed the association between the MBL2 gene and type 2 diabetes." (PMID 24376633, 2013). "Frequencies of MBL2 genotypes were similar in Swedish adults with type 2 diabetes and subjects in the general European population." (PMID 31117958, 2019). "Additional studies are needed to investigate the impact of the MBL2 gene on specific type 2 diabetes related pathways." (PMID 24376633, 2013). "Our study did not indicate whether the MBL2 gene influences type 2 diabetes by affecting insulin secretion or insulin action." (PMID 24376633, 2013).
Autoimmunity (5 papers, 2012 to 2023). The occurrence of an immune reaction against the organism's own cells or tissues. "In this sense, the objective of the present study was to identify polymorphisms in important mediators of the immune response (FOXP3, IFNG, IL6, IL8, IL10, MBL2, CRP, TGFΒ1 and TNFA) in association with ANAs, which could contribute to the development of autoimmunity in hepatitis C." (PMID 32743104, 2020). "This MBL2 promoter variation has a significant down-regulating effect on the serum MBL concentration, leading to ineffective clearance of apoptotic cells and the spread of self-antigens, permitting an immune response toward autoimmunity and tissue damage." (PMID 30508004, 2018).
Candida infection (5 papers, 2013 to 2020). "It has been shown that polymorphisms in the MBL2 gene, particularly at codon 54 (variant allele B; wild-type allele designated as A), impact upon host susceptibility to Candida infection." (PMID 25143944, 2014). "This may contradict a previous study that showed an association between MBL2 genotype and incidence of fungal infections, including Cryptococcus, Aspergillus, and Candida infections." (PMID 33362211, 2020). "On the contrary, in our study, 4 patients with fungal infection carried the MBL2 deficient genotype; 2 had Aspergillus and Mucor pneumonia (both died as a consequence of their fungal infection); 1 had candidemia; and 1 had disseminated mucocutaneous Candida infection." (PMID 24886325, 2014).
chronic obstructive pulmonary disease (5 papers, 2015 to 2026). A chronic and progressive lung disorder characterized by the loss of elasticity of the bronchial tree and the air sacs, destruction of the air sacs wall, thickening of the bronchial wall, and mucous accumulation in the bronchial tree. "In British adults with chronic obstructive pulmonary disease, the risk of infective exacerbations was significantly lower in patients with MBL2 genotypes that predicted low MBL levels." (PMID 31117958, 2019). "The disease‐modifying role of MBL2 has been also correlated with the frequency of respiratory infection‐associated hospital admissions in chronic obstructive pulmonary disease patients, implicating a putative beneficial role for MBL replacement therapy in this disease entity." (PMID 32246830, 2020).
colorectal cancer (5 papers, 2015 to 2023). A primary or metastatic malignant neoplasm that affects the colon or rectum. "Similarly, elevated plasma MBL2 levels in colorectal cancer patients have been identified as an indicator of unfavorable patient survival." (PMID 37953280, 2023). "In general, in colorectal carcinoma progression, C4B, MBL2, CARD9, and TNFRSF8 affected DSS." (PMID 35456394, 2022).
cryptosporidiosis (5 papers, 2012 to 2023). Intestinal infection with organisms of the genus Cryptosporidium. "Briefly, serum mannose binding lectin deficiency and mbl2 structural gene mutations increased the risk for cryptosporidiosis." (PMID 22685452, 2012). "In 5% of the world’s population, polymorphisms in the MBL2 gene create low MBL-producing MBL2 genotypes, which may lead to an increased susceptibility to particular diseases, including cryptosporidiosis." (PMID 37325809, 2023). "Polymorphisms in the MBL2 gene can lead to the low production of MBL, making children more prone to diarrheal diseases, including cryptosporidiosis." (PMID 37764167, 2023).
glioma (5 papers, 2013 to 2024). A benign or malignant brain and spinal cord tumor that arises from glial cells (astrocytes, oligodendrocytes, ependymal cells). "In this prospective study combining data from three large cohorts, we observed significant associations between SNPs in MBL2 gene and risk of glioma." (PMID 23637788, 2013). "MBL2 haplotypes associated with risk of glioma in 3 prospective studies." (PMID 23637788, 2013). "We observed an association with a tagging SNP on MBL2 (rs1982266; OR = 0.36, 95% CI = 0.19–0.66 for homozygous recessive compared to homozygous dominant, test for trend p = 0.003) and glioma risk in our preliminary analysis of SNPs selected from HapMap that cover 10 genes in the complement pathway." (PMID 23637788, 2013). "Association between MBL2 SNPs and risk of glioma in 3 prospective cohort studies." (PMID 23637788, 2013). "MBL2 is a mannose-binding protein that plays a critical role in the immune response, and is capable of binding glioma cells in vitro." (PMID 38542389, 2024). "Statistically significant associations were observed for two SNPs in the mannose-binding lectin 2 (ML2) gene and risk of glioma (rs1982266 and rs1800450, test for trend p = 0.003 and p = 0.04, respectively, using the additive model)." (PMID 23637788, 2013). "We observed a strong association between two MBL2 polymorphisms which are not in high linkage disequilibrium and risk of glioma." (PMID 23637788, 2013). "SNPs in MBL2 and the complement pathway have not been examined in relation to risk of glioma." (PMID 23637788, 2013). "Additionally, six targets are regulated by our miRNAs both in glioma and meningioma: CR2, KNG1, PROS1, F9, MBL2 and F11, while different miRNAs are dysregulated in each cancer type." (PMID 32545233, 2020).
pneumonia (5 papers, 2014 to 2025). An acute, acute and chronic, or chronic inflammation focally or diffusely affecting the lung parenchyma, caused by an infection in one or both of the lungs (by bacteria, viruses, fungi, or mycoplasma.). "There was also a low incidence of pneumonia (5.6% of all patients), which occurred more frequently in the MBL2 variant group, 10.5% versus 3.8%, RR: 2.8 (0.4-18.4), p = 0.28." (PMID 24886325, 2014). "Similarly, in our series more severe infections and a greater number of episodes of pneumonia were found in patients with variant MBL2." (PMID 24886325, 2014).
vitiligo (5 papers, 2012 to 2024). Generalized well circumscribed patches of leukoderma that are generally distributed over symmetric body locations and is due to autoimmune destruction of melanocytes. "Genetic association models for the MBL2 gene rs1800450 SNP with vitiligo risk (total n = 390, controls = 300, vitiligo patients = 90, adjusted by age and sex)." (PMID 38404462, 2023). "Correlation matrix between vitiligo patients’ demographic data, clinicopathological features, and the MBL2 gene rs1800450 SNP genotyping." (PMID 38404462, 2023). "Our findings highlighted that the rs1800450 SNP on the MBL2 gene has no role in the disease susceptibility to autoimmune skin diseases, such as psoriasis and vitiligo, among Egyptian patients." (PMID 38404462, 2023). "Finally, mannose-binding protein C (MBL2) was downregulated in progressive vitiligo compared to healthy controls, while it was upregulated in stable vitiligo patients compared to controls." (PMID 38715599, 2024).
AIDS (4 papers, 2018 to 2021). A syndrome resulting from the acquired deficiency of cellular immunity caused by the human immunodeficiency virus (HIV). "In addition, variants in the MBL2 gene have also been shown to be related to disease progression to AIDS and death." (PMID 34154540, 2021). "Therefore, the aim of this study was to clarify the impact of MBL expression type defined by MBL2 genotypes on the risk of developing HIV/AIDS-related OIs, especially PCP, in a natural history HIV cohort in northern Thailand." (PMID 33362211, 2020). "Variations of the MBL-2 allele have been associated with HIV infection and AIDS progression, likely due to the role of MBL-2 in macrophage-related innate and adaptive immunity." (PMID 30441796, 2018). "Researchers have also found that the toll-interacting protein (TOLLIP) and mannose-binding lectin 2 (MBL2) genes may also play a vital role in HIV infection and the progression to AIDS." (PMID 34154540, 2021).
dental caries (4 papers, 2017 to 2025). The decay of a tooth, in which it becomes softened, discolored, and/or porous. "The prior study identified a correlation between polymorphism in the MBL2 gene and dental caries in Iranian adults." (PMID 41195299, 2025). "Herein, we designed a systematic review and meta-analysis to evaluate the association of DEFB1 (rs11362, rs1799946, and rs1800972) and MBL2 (rs7096206 and rs1800450) polymorphisms with the susceptibility to dental caries (DC) in children." (PMID 36832361, 2023).
fungal infections (4 papers, 2014 to 2020). "It has been reported that a number of major SNPs are associated with susceptibility of fungal infections and diseases, including MBL2, TLR1/4/6/9, CARD9, CXCL2, DECTIN1, IL4/10/15/2, and HLA." (PMID 33362211, 2020). "Low-producer MBL2 genotypes were associated with an increased number of fungal infections in ASCT patients, which would suggest that MBL has a protective role against such infections." (PMID 24886325, 2014). "The incidence of fungal infections in the variant MBL2 group (3 Candida albicans, 1 Mucor, 1 Aspergillus) was statistically significantly higher than in the MBL2 wild-type group (1 Candida spp), RR = 11.5 (95% CI: 1.3-93.7, p = 0.016), as confirmed in a multivariate analysis." (PMID 24886325, 2014).
liver disease (4 papers, 2013 to 2024). "The manifestation of liver disease can be influenced by genetic modifiers, including the protease inhibitor gene, mannose-binding lectin 2 gene, beta-TGF gene, and glutathione S-transferase 1 gene." (PMID 38473009, 2024).
lung carcinoma (4 papers, 2009 to 2023). "Also, the EGFR gene polymorphic simple sequence repeat (SSR) length, the Y/X polymorphism of the innate-immunity gene MBL2 with haplotypes, and glutathione-related genes have been associated with improved lung cancer survival." (PMID 19478952, 2009). "The second panel, comprising CFHR5, C9, and MBL2 proteins, shows potential in evaluating the occurrence of metastasis in patients with early-stage lung cancer." (PMID 37953280, 2023).
ovarian carcinoma (4 papers, 2014 to 2022). A malignant neoplasm originating from the surface ovarian epithelium. "The O/O and A/O MBL2 genotypes (where O corresponds to any of the variant alleles commonly called D, B, and C, localized to exons 52, 54, and 57 of the first exon, respectively, while A refers to the wild type) were found to be associated with ovarian cancer." (PMID 35326694, 2022). "Additionally, local expression of MBL2 genes is higher in women with ovarian cancer than in controls." (PMID 34944885, 2021). "The local expression of MBL2 and MASP2 genes was higher in women with ovarian cancer compared with controls." (PMID 25038892, 2014).
vaginal infection (4 papers, 2014 to 2020). "This is the first comprehensive and systematic meta-analysis undertaken for the evaluation of MBL2 gene polymorphisms in susceptibility to acute and recurrent nature of vaginal infections." (PMID 32269261, 2020). "Several studies in women populations have found a significant association between recurrent vaginal infections, especially vulvovaginal candidiasis and bacterial vaginosis, with the presence of codon 54 polymorphisms of MBL2 gene." (PMID 28824344, 2017). "However, MBL2 gene structural polymorphisms alone could be responsible for the defective binding of MBL to Candida via its lectin domain at early phase of vaginal infection by the fungus." (PMID 29850562, 2018). "On the other hand, the MBL2 structural gene variants alone could be responsible for diminished binding of the MBL protein to Candida cells via its lectin domain, at the early phase of defense against Candida during vaginal infection by the fungus." (PMID 25143944, 2014).
vulvovaginal candidiasis (4 papers, 2005 to 2023). Infection of the vulva and vagina with a fungus of the genus CANDIDA. "This systematic review and meta-analysis were performed to assess the association between MBL2 codon 54 genotype and vulvovaginal candidiasis (VVC) or recurrent VVC (RVVC)." (PMID 25143944, 2014). "Low serum levels of MBL and MBL2 genetic variants are associated with infection in a range of contexts including recurrent infection in children and adults, recurrent vulvovaginal candidiasis, recurrent miscarriage and autoimmunity in common variable immunodeficiency disease." (PMID 15723707, 2005). "The present study aimed to identify the possible influence of codons 54 and 57 polymorphisms of MBL2 gene on the presence of CVI including bacterial vaginosis, vulvovaginal candidiasis, and trichomoniasis in Mexican women." (PMID 28824344, 2017).
chorioamnionitis (3 papers, 2005 to 2018). A morphologic finding indicating inflammation of the fetal sac membranes. "The association between MBL2 codon 54Asp and histologic chorioamnionitis suggests that this allele may result in low MBL levels, impaired opsonisation and clearance of pathogens, thus facilitating the development of chorioamnionitis." (PMID 15723707, 2005). "MBL-2 presumably functions as part of the host defense system, including DEFB1, which prevents or limits infections that cause chorioamnionitis and PPROM." (PMID 30290772, 2018). "Our data support the role of IL10, MBL2 and TNFRSF6 variants in determining the risk of histologic chorioamnionitis." (PMID 15723707, 2005). "The differences in genotype distribution for IL10 and MBL2 may be of biologic importance in the pathogenesis of histologic chorioamnionitis." (PMID 15723707, 2005). "In preterm women without histologic chorioamnionitis frequencies for the IL10-1082A/-819T/-592A (ATA) haplotype, MBL2 codon 54Asp (the MBL 'B' allele), TNFRSF6-1377A/-670G (AG) haplotype and TGFB1-800G/-509T (GT) homozygosity were similar to reported Caucasian controls." (PMID 15723707, 2005).
Cirrhosis (3 papers, 2017 to 2026). A chronic disorder of the liver in which liver tissue becomes scarred and is partially replaced by regenerative nodules and fibrotic tissue resulting in loss of liver function. "Recently, it was reported that the presence of mutant alleles in the promoter region (−221 C>G) of the MBL2 gene could protect against the more severe forms of the liver injury (cirrhosis and HCC), and a better liver function was shown as associated with high MBL serum levels." (PMID 28408790, 2017).
Crohn disease (3 papers, 2016 to 2018). A gastrointestinal disorder characterized by chronic inflammation involving all layers of the intestinal wall, noncaseating granulomas affecting the intestinal wall and regional lymph nodes, and transmural fibrosis. "In the present study, the analysis of MBL2 polymorphisms revealed an association between three variants, rs930508, rs1800450 and rs5030737, and a reduction in mannose-binding lectin serum levels in Crohn’s disease patients." (PMID 27404661, 2016). "This study will enable us to determine the relationship between MBL2 and NOD2 in Crohn’s disease and the way in which each affect the other by studying the signalling pathways." (PMID 27404661, 2016).
Dengue hemorrhagic fever (3 papers, 2012 to 2019). A serious condition caused by Dengue virus infection. "For DENV infection, a genetic association of the exon 1 polymorphisms of the human MBL gene (MBL2) with dengue hemorrhagic fever has been suggested because variant alleles and haplotypes related to low production levels of MBL are associated with the severity of DENV-induced diseases." (PMID 30104482, 2018).
Giardia infection (3 papers, 2017 to 2022). "The data presented here further indicate that the combination of complement activation through Mbl2 and parasite-specific IgA’s is crucial to combat a Giardia infection." (PMID 28819174, 2017). "The most important downstream effectors of the IL-17A response, that have been shown to play a critical role in the clearance of a Giardia infection, are the activation of the complement system by mannose-binding lectin 2 (MBL2) and the production and secretion of parasite-specific IgA’s4,6,7." (PMID 34011991, 2021). "The literature suggests that mast cells are recruited via activation of the complement lectin pathway since mice lacking mannose-binding lectin 2 (MBL2) and complement factor 3a receptor (C3aR) expression are impaired in mast cell recruitment during Giardia infection." (PMID 36211380, 2022).